IL6 (interleukin 6)
Diseases named in the same sentence as IL6 in open-access papers (continued):
Sharing a sentence is not in itself a finding about the gene and the disease.
atrial fibrillation (125 papers, 2008 to 2026). A disorder characterized by an electrocardiographic finding of a supraventricular arrhythmia characterized by the replacement of consistent P waves by rapid oscillations or fibrillatory waves that vary in size, shape and timing and are accompanied by an irregular ventricular response. "This study revealed that macrophages that infiltrate the atria following surgery release interleukin-6 which causes aberrant calcium release events and postoperative atrial fibrillation." (PMID 40048254, 2025). "A study reported that TLR8 was correlated with levels of IL6, IL1β, and a greater inflammatory response, which is an important mechanism that causes atrial fibrillation." (PMID 36671813, 2023). "Inflammatory markers such as c-reactive protein (CRP) and interleukin-6 have been associated with an increased risk of atrial fibrillation and have been linked to chronic atrial fibrillation, left atrial dilation, and the promotion of a pro-thrombotic state." (PMID 37568436, 2023). "Expanded visceral adipose tissue produces less serum adiponectin but secretes more pro-inflammatory cytokines, such as serum interleukin (IL)-6, which has been linked to subclinical atherosclerosis and atrial fibrillation." (PMID 35328216, 2022). "Patients who underwent cardiac operation with increased inflammatory levels, including an elevated white blood cell count and interleukin-6 levels, have a greater risk of atrial fibrillation." (PMID 36247462, 2022). "In bivariate analyses female sex, older age, higher NIHSS score, SAP, atrial fibrillation, lower mHLA-DR expression as well as higher IL-6-levels on day 1 were associated with shorter survival time." (PMID 31269910, 2019). "Further adjustment for atrial fibrillation, IL-6, vWF and FEV1 attenuated the association but risk remained significantly reduced in the top quintile (≥ 0.87 mmol/l) compared with the lowest quintile [HR 0.62 (0.40, 0.97)]." (PMID 29663176, 2018). "Evidence indicates that atrial fibrillation after coronary artery bypass grafting is associated with increase in IL-6 in patients." (PMID 26977143, 2016). "Given IL-6's role in atrial remodeling and its association with left atrial enlargement, IL-6 blockade may offer a novel strategy to diminish atrial inflammatory matrix and slow progression of atrial fibrillation." (PMID 41608286, 2026). "In addition, intraperitoneal injection of IL-6 in rats increased susceptibility to atrial fibrillation." (PMID 36059969, 2022). "Regardless of specific aetiology and organ localization, systemic inflammation, via IL‐6 elevation, rapidly induces atrial electrical remodelling and electrical instability thus increasing susceptibility to atrial fibrillation, by downregulating cardiac connexins." (PMID 34773379, 2021). "Another study revealed that among patients receiving isolated elective coronary artery bypass grafting, those with an IL-6 gene promoter variant associated with high postoperative IL-6 levels were more likely to experience postoperative atrial fibrillation as a major postoperative complication." (PMID 25722960, 2015). "QT prolongation is associated with systemic inflammatory response characterized by IL-6 upregulation and administration of IL-6 receptor blocking antibody (Tocilizumab) had yielded successful outcomes in decreasing the risk of QT interval related tachyarrhythmias including atrial fibrillation." (PMID 37120772, 2023). "In our study, IL‐6 not only showed a significant association with AF in comparison to the NSR group, but also a statistically significant graded increase in the serum level in subclinical and chronic subgroups of atrial fibrillation." (PMID 33335617, 2020). "Studies indicate that interleukin-6 (IL-6) serves as an independent risk factor for the occurrence of atrial fibrillation (AF), playing a crucial role in both the initiation and persistence of AF." (PMID 39981345, 2025).
atrial fibrillation (continued). "Elevated IL-6 levels are also commonly found in patients with atrial fibrillation, and this cytokine is believed to influence electrical conduction in the heart by altering gap junctions and intercellular communication." (PMID 40901119, 2025). "Further indirect evidence supporting a role for IL6-induced arrhythmias comes from a recent mouse model of atrial dilation, where blockade of IL6 trans-signaling attenuated the propensity to atrial fibrillation." (PMID 39596280, 2024). "Sustained inflammatory state in COVID-19-induced atrial fibrillation documented by marked upregulation of IL-6, CRP (C-reactive protein) and plasma viscosity provides a forewarning for occurrence of thromboembolism and stroke in these patients." (PMID 37120772, 2023). "Our study confirms that using MLOP was characterized by significantly lower levels of IL-6 at the end of surgery and a lower incidence of low cardiac output syndrome and postoperative atrial fibrillation than ROP." (PMID 37803334, 2023). "A study has shown high IL-6 levels in most patients with DCM; high IL-6 levels were associated with low LVEF, atrial fibrillation, and poor clinical outcomes." (PMID 37919409, 2023). "Studies of humans with atrial fibrillation identified an activation of inflammatory factors such as IL6 and TNFα, and an increased number of CD3-positive T cells." (PMID 36928240, 2023). "This is in line with prior studies showing elevated IL-6 and IL-15 in patients with atrial fibrillation." (PMID 37005652, 2023). "Similarly, in this patient population, atrial fibrillation (AF) showed a significant association with raised levels of IL-6, indicating the unique impact IL-6 has on the pathophysiology of AF." (PMID 37637634, 2023). "An observational study showed that higher IL-6 plasma levels were found in half of HF patients and were associated with reduced left ventricular ejection fraction (LVEF), atrial fibrillation, and poorer clinical outcomes." (PMID 35402550, 2022). "In the large heterogeneous HF cohort, more than 50 per cent of patients found that IL-6 levels were elevated and were associated with iron deficiency, reduced LVEF, atrial fibrillation, and poor clinical outcomes." (PMID 35341142, 2022). "Following the event of myocardial ischemia, local as well as systemic inflammation arises, which causes the release of various inflammatory factors such as IL-6 and CRP, which have been independently associated with the development of atrial fibrillation." (PMID 35008432, 2021). "Group 1 patients (normal IL-6) had a higher frequency of atrial fibrillation compared to Group 2 (83.3% vs. 61.9%; p = 0.036)." (PMID 33535417, 2021). "Female sex, older age, atrial fibrillation, SAP, higher NIHSS score, lower mHLA-DR expression and higher IL-6 levels were associated with shorter survival time in bivariate analysis." (PMID 31269910, 2019). "The increased mRNA expressions of classic inflammatory factors (i.e., interleukin-1 beta, interleukin 6, and tumor necrosis factor-alpha) in AF(+)thrombus(+) group further validated the correlation between inflammation and thrombi in atrial fibrillation." (PMID 29595637, 2018). "To clarify the correlation between inflammation and thrombosis in atrial fibrillation, we detected the mRNA expressions of classic inflammatory molecules (i.e., IL-1β, interleukin-1 beta; IL-6, interleukin 6; TNF-α, tumor necrosis factor-alpha)." (PMID 29595637, 2018). "A variety of studies have also implicated inflammation in having an aetiological role in the initiation and perpetuation of atrial fibrillation due to evidence of raised inflammatory markers such as interleukin-6 and C-reactive protein in AF patients." (PMID 23401843, 2013). "Patients with atrial fibrillation demonstrate evidence of inflammation, with elevated levels of inflammatory markers, including C-reactive protein, interleukin-6, and tumor necrosis factor-α." (PMID 21896397, 2012).
atrial fibrillation (continued). "Elevation of tumor necrosis factor and IL-6 occurs one to two days following intravenous administration of bisphosphonates and can increase the incidence of atrial fibrillation." (PMID 21838908, 2011). "Although most variables, (except IL-6) were significant in univariate analysis (p ≤ 0.047), only atrial fibrillation (AOR = 2.31, 95% CI: 1.09-2.84, p = 0.021) and creatinine (AOR = 1.40, 95% CI: 1.00-1.95, p = 0.048) remained independent predictors in the multivariate model." (PMID 42279490, 2026). "Markers of cardiovascular (atrial fibrillation), renal (creatinine, urea), immune-inflammatory (IL-6, CRP, ESR, procalcitonin, presepsin), metabolic (FBG), hepatic (AST, ALT), and comorbidity burden (CCI) domains were analyzed using logistic and LASSO regression with bootstrap validation." (PMID 42279490, 2026). "Colchicine, a recognized anti-inflammatory agent, has demonstrated mechanistic effects in atrial fibrillation in animal studies, including inhibition of IL-6 release triggered by IL-1β, attenuation of subsequent atrial fibrosis, and modulation of ion channel gene expression and signaling pathways." (PMID 41608286, 2026). "Also post-operative atrial fibrillation (POAF) has determined correlation with inflammatory processes associated with elevated TNF-α and IL-6 levels." (PMID 41574188, 2025). "The mechanism may be that it can regulate the balance of autonomic nervous system and reduce systemic and local inflammatory response represented by IL-6, and finally improve postoperative atrial fibrillation." (PMID 38166634, 2024). "In a previous study on atrial fibrillation, hypertrophic adipocytes and activated macrophages secreted tumor necrosis factor‐α and interleukin‐6 (IL‐6) to activate NOD‐like receptor family protein‐3 (NLRP3) inflammatory pathway and promote atrial fibrosis and electrical remodeling." (PMID 37707300, 2023). "Infiltration of CD68-positive macrophages and increased expression of IL-6 and transforming growth factor beta (TGFβ), inflammatory factors mainly derived from epicardial adipose tissue, were seen in atrial tissue from patients with atrial fibrillation (AF)." (PMID 36405582, 2022). "Here, we hypothesize that IL-6-mediated-Ca2+ handling abnormalities contribute to atrial fibrillation (AF) in sterile pericarditis (SP) rats, an animal model of POAF." (PMID 34975847, 2021). "Inflammatory mediators produced by mononuclear macrophages, such as TNF-α and IL-6, promote atrial myocyte degeneration and fibrosis and slow conduction, thereby contributing to both structural and electrical remodeling that can initiate and sustain atrial fibrillation." (PMID 41608286, 2026). "Therefore, IL-6 and hsCRP may be used as reference biomarkers to assess the duration of atrial fibrillation." (PMID 34712708, 2021). "Furthermore, previous studies have shown associations between CRP and cytokines such as IL-6 and atrial fibrillation and other arrhythmias in the absence of CAD, raising the possibility of a direct electrophysiological effect." (PMID 31234795, 2019). "In patients with DCM and co-existing AF, a weaker effect of atorvastatin concerning the reduction of IL-6 and NT-proBNP concentration was observed than in patients without atrial fibrillation." (PMID 20178563, 2010). "Left atrial myocardial fibrosis was positively correlated with the level of proinflammatory and profibrotic cytokines/chemokines, IL‐6, MCP‐1, and TNF‐α, in EAT and myocardial fibrosis is a known substrate for atrial fibrillation." (PMID 39167271, 2025). "One patient in the normal IL-6 group had a MACE, and three patients developed new-onset atrial fibrillation." (PMID 40491666, 2025). "Circulating biomarkers reveal a steady increase in pro-inflammatory cytokines (IL-6, IL-17, TNF-α) and a decrease in regulatory T-cell fractions in non-paroxysmal atrial fibrillation." (PMID 41156185, 2025).
atrial fibrillation (continued). "Similar results were obtained to the LAVI cutoff stratification, with an additional significant increase in H3Cit, IL-6, D-dimers, soluble P-selectin, and ICTP in patients with any history of atrial fibrillation." (PMID 38922424, 2025). "In clinical studies, needle-based auricular VNS decreased serum IL-6 in patients with lung lobectomy; taVNS decreased serum TNF-α in patients with paroxysmal atrial fibrillation." (PMID 34138761, 2021). "Pro‐inflammatory cytokines, such as IL‐6 and TNF‐α, are considered key mediators of inflammation‐related atrial fibrillation." (PMID 32441464, 2020). "Elevated levels of CXCL8, CCL11, CCL2, CXCL10, IL-1β, IL-6, TNF-α, IFN-γ, IL-17, IL-1Ra, IL-4, IL-9, FGF-basic, PDGF, G-CSF, and GM-CSF were observed in the Atrial fibrillation patient, in contrast to uninfected controls." (PMID 29370812, 2018). "Predictors of HF hospitalization included IL6 levels >4.03pg/ml, NYHA class III/IV, EF <20%, hemoglobin <12g/dL and atrial fibrillation and were consistent with findings from other CRT cohorts." (PMID 28388657, 2017). "However, PAI-1 did not remain an independent variable in the best diagnostic model, which consisted of age, face- arm- speech test (FAST), atrial fibrillation, and three other serum markers (protein S100B, MMP-9 and IL-6)." (PMID 39001884, 2024). "Neither the IL-6 nor the ET-1 levels were correlated with the presence of atrial fibrillation in either of the two groups." (PMID 34683106, 2021). "In addition to the four most predominant diseases in the clinic, IL-6 can also affect diabetic cardiomyopathy (DCM) and atrial fibrillation (AF)." (PMID 34504432, 2021). "In contrast, inflammation assessed based on the IL-6 and ET-1 value was not correlated with the presence of atrial fibrillation in the group of patients with microvascular involvement or in the group of patients with macrovascular coronary lesions." (PMID 34683106, 2021). "The role of inflammation in initiating and propagating non‐valvular atrial fibrillation has been suggested in several studies using inflammatory biomarkers [like high‐sensitivity C‐reactive protein (hs‐CRP), Interleukin‐6 (IL‐6), Soluble CD‐40 Ligand (sCD‐40L)] as a measure of systemic inflammation." (PMID 33335617, 2020). "In this review we highlight current reports of IL-6 involvement in the pathogenesis of cardiac dysfunctions associated with increased vulnerability to fatal ventricular arrhythmias (long QT syndrome or LQTS) or increased morbidity (atrial fibrillation or AF) and mortality." (PMID 30666212, 2018). "Interestingly, atrial fibrillation (AF) and COVID-19 infection appear to share some pathophysiological features, both being driven by an immune response, with inflammatory markers, such as C-reactive protein and cytokine interleukin (IL)-6, correlating with disease severity and mortality." (PMID 36755799, 2023). "There was a statistically significant graded increase of serum IL‐6 level from the NSR to the SCAF (vs NSR: 6.8 ± 3.9 vs 4.0 ± 2.2 pg/mL, P = .03), and chronic AF subgroups (vs NSR: 9.3 ± 6.5 vs 4.0 ± 2.2 pg/mL, P < .01; vs SCAF: 9.3 ± 6.5 vs 6.8 ± 3.9, P = .05) of atrial fibrillation." (PMID 33335617, 2020). "In a study of 106 outpatients with atrial fibrillation (AF), it was reported that AF patients have higher levels of IL-6, CRP, TF, and plasma viscosity compared with controls, and significant correlations were reported between these inflammatory markers (IL-6, CRP) and prothrombotic plasma markers." (PMID 19936194, 2008). "In the high IL-6 group, MACE and new-onset atrial fibrillation did not occur (P=1.00 and P=0.68, respectively)." (PMID 40491666, 2025). "“Normal” values are age and disease state-dependent, but for perspective, the case-matched controls with no arrhythmias in our atrial fibrillation study had mean DROMS 310 Carr units, Eh CySH −77 mV, Eh GSH −154 mV, IL-1β 0.4 pg/mL, IL-6 3.9 pg/mL, TNFα 5.5 pg/mL, and hsCRP 3.6 μg/mL." (PMID 20369058, 2010).
chorioamnionitis (125 papers, 1997 to 2026). A morphologic finding indicating inflammation of the fetal sac membranes. "Amniotic and cervicovaginal IL-6 levels have been linked with preterm birth and are elevated in cases of preterm labor associated with histologic chorioamnionitis." (PMID 41598260, 2026). "IL-6, a cytokine with both pro-inflammatory and anti-inflammatory roles, has been associated with intra-amniotic infection and neonatal sepsis." (PMID 39857911, 2025). "When antenatal risk factors are present, such as chorioamnionitis, IL-6 levels can be measured in umbilical cord blood as its level increases significantly, highlighting its important role in the acute immune response." (PMID 41010644, 2025). "Increasing levels of infection-mediated pro-inflammatory cytokines, including TNF, IL-1β, IL-6, and IL-2, have been linked to chorioamnionitis and adverse pregnancy outcomes." (PMID 38877443, 2024). "Clinical evidence reveals that compared with controls, infants exposed to chorioamnionitis and admitted to the neonatal intensive care unit had higher levels of IL‐6, IL‐8, and RANTES in cord blood, which was associated with neurologic abnormalities." (PMID 39575516, 2024). "As a result, CRP can be used as a screening diagnostic for chorioamnionitis since it is an indirect biomarker of IL-6 secretion." (PMID 37919654, 2023). "In summary, maternal diabetes and birth weight are associated with leptin while chorioamnionitis is associated with IL-6." (PMID 35197933, 2022). "Of the pre-specified risk factors, only maternal chorioamnionitis and neonatal antibiotic use were associated with IL-6 levels." (PMID 35197933, 2022). "In contrast, clinically diagnosed maternal chorioamnionitis was associated with a 2-fold increase in IL-6." (PMID 35197933, 2022). "Increased maternal IL-6 levels have been related to the development and severity of different pregnancy-associated complications such as pre-eclampsia or chorioamnionitis." (PMID 36012236, 2022). "Apart from IL-8, IL-6 level was also elevated in the CSF of infants exposed to chorioamnionitis in association with an increased risk of posthemorrhagic hydrocephalus." (PMID 32961661, 2020). "Elevated levels of pro-inflammatory cytokines such as TNFα, IL-1, IL-12, IL-6, and IL-2 have been linked to chorioamnionitis and therefore elevated levels of these cytokines serve to identify potential pregnancy complications." (PMID 33123496, 2020). "A study on placental (fetal) genotype from API cases, also focusing on immune-associated genes, found an association between chorioamnionitis, a promoter variant in interleukin 6 (IL6), methylation of the IL6 promoter and IL6 gene expression." (PMID 33281808, 2020). "On multivariate analyses, an elevated plasma IL-6 level was significantly associated with intra-amniotic infection and imminent preterm delivery after adjusting for confounders, including high serum CRP levels and short cervical length." (PMID 29743041, 2018). "We found that plasma IL-6 has a worse overall diagnostic performance than that of AF IL-6 in predicting intra-amniotic infection." (PMID 29743041, 2018). "Maternal plasma IL-6 independently predicts intra-amniotic infection in women with preterm labor; however, it has worse diagnostic performance than that of AF IL-6 and similar performance to that of serum CRP." (PMID 29743041, 2018). "In conclusion, maternal plasma IL-6 independently predicts intra-amniotic infection in women with preterm labor; however, it has worse diagnostic performance than that of AF IL-6 and similar performance to that of serum CRP." (PMID 29743041, 2018). "Lastly, IL-6 is well known marker for inflammatory condition, and the elevated AF concentrations of IL-6 has been reported to be associated with intra-amniotic infection and adverse pregnancy outcomes." (PMID 26076029, 2015). "We then examined the association of admission white blood cell count and IL-6 and IL-8 levels with histologic chorioamnionitis." (PMID 22412842, 2012).